ALK (ALK receptor tyrosine kinase)
Diseases named in the same sentence as ALK in open-access papers (continued):
Sharing a sentence is not in itself a finding about the gene and the disease.
tumor (continued). "Furthermore, we validated that ALK expression by IHC is frequent, and 51% of the tumours exhibit strong staining for ALK and a positive IHC staining clearly correlates to MCPyV positivity." (PMID 34029351, 2021). "The ENIGMA+ trial, a biorepository of ALK-rearranged NSCLC patients in order to further understand the interactions between the tumor and host immunity, is now open to researchers in this field in order to foster development of effective immune-based treatment approaches for ALK-rearranged NSCLC." (PMID 33806977, 2021). "Indeed, the combination of ALK and MEK inhibition was highly effective at suppressing tumor growth in a preclinical model of EML4‐ALK NSCLC." (PMID 34058070, 2021). "To get further information about the genomic regions that are affected by aberrant methylation in ALK tumor cells we performed genomic region enrichment analysis on differentially methylated promoter-associated CpGs tiled into 200-bp genomic regions using locus overlap analysis (LOLA)." (PMID 33310759, 2021). "Moreover, variable degrees of intra-patient tumor diversity were observed, except in P46 epithelial CTCs which harbored recurrent altered regions such as chromosome 2 (ALK and MYCN gains), chromosome 6 (CCND3 gain), and chromosome 17 (SEPT9 gain)." (PMID 34272470, 2021). "We identified SNVs in the exo-DNA that were not present in tumor DNA at onset of disease, in particular mutations of ALK, ATRX, NF1, and TERT genes, probably coming from other tumor sites." (PMID 33915956, 2021). "Therefore, the development of a new agent with high selectivity for oncogenic ALK-fusion signaling was necessary as a next step to achieve further long-term tumor control with less toxicity." (PMID 34446006, 2021). "Furthermore, a similar fraction of Ctrls and ALK tumor-free thymocytes expressed the TCRβ, whereas the TCRβ+ fraction was absent in cells isolated from ALK tumors." (PMID 33310759, 2021). "KEYNOTE-042 included NSCLC with locally advanced or metastatic disease without previous treatment and without a driving mutation in EGFR or ALK translocation, and with PD-L1 tumor proportion score (TPS) of 1% or greater." (PMID 33171686, 2020). "Even if the EGFR mutation is negative, due to the small number of remaining tumour cells available for analysis, samples often cannot be tested for ALK." (PMID 33425389, 2020). "This difference of MAX expression in ALK-positive ALCL between the datasets may be attributed to the percentage of tumor cells in each sample." (PMID 32587329, 2020). "Such an ALK-induced PD-L1 upregulation may potentially confer an immunosuppressive tumor microenvironment contributing to tolerance and immune evasion in cancer." (PMID 32059449, 2020). "Targeted therapies directed at tumour cells harbouring epidermal growth factor receptor (EGFR) gene mutations, anaplastic lymphoma kinase (ALK) gene rearrangements, ROS proto-oncogene 1 (ROS1) gene fusions, and B-Raf proto-oncogene (BRAF) gene mutations have produced impressive results." (PMID 32907572, 2020). "Meanwhile, ALK fusion in circulating tumor RNA (ctRNA) was recognized via the method." (PMID 32543087, 2020). "Molecular aberrations involving various driver mutations including ALK, ROS1, KRAS, IDH1/2 and JAK2 may impact thrombotic risk in various tumor types." (PMID 32707653, 2020). "Anaplastic lymphoma kinase (ALK) tumours represent around 8% of NSCLC." (PMID 33270840, 2020). "Upon laser irradiation, significant ALK-gene inhibition occurred only at the tumour site." (PMID 33270840, 2020). "All patients were diagnosed with an ALK rearrangement in their tumor biopsy." (PMID 32290439, 2020). "This may be explained by tumor cells harboring ALK rearrangement decreasing or disappearing after effective therapy." (PMID 32974126, 2020).
tumor (continued). "The increased expression of hepatocyte growth factor (HGF) and its physiological receptor tyrosine kinase MET have been shown to be linked to acquired resistance to various tyrosine kinase inhibitors (TKIs), and this phenomenon has been observed in some ALK-positive NSCLC tumour tissues." (PMID 32041944, 2020). "Molecular testing (circulating tumor ctDNA by high-throughput next-generation sequencing) revealed no EGFR mutations or ALK rearrangements." (PMID 33285759, 2020). "New targeted therapies for mutations in EGFR, ALK (anaplastic lymphoma kinase), immunotherapy PD-1 (programmed death-1) receptor, and programmed death ligand 1 (PDL-1) have shown promising results in both primary tumor and BM but require further studies." (PMID 31900168, 2020). "A multivariable analysis indicated that concomitant oncogene mutations and tumor-suppressor gene mutations were both negative factors influencing the efficacy of crizotinib in ALK rearrangement NSCLC." (PMID 32974126, 2020). "Importantly, the concordance for ALK and EGFR mutations across 18 patients was 100%, showing that tumor exosomes derived from pleural fluid can be used to guide treatment with targeted agents." (PMID 33139621, 2020). "As tumour-suppressive miRNAs, the expression of miR-29a, miR129-2, Hsa-miR-203, miR-195, miR-497, miR125b, and miR150 was suppressed by promoter hypermethylation in ALK-positive ALCL." (PMID 33160401, 2020). "We showed that concomitant mutations, irrespective of oncogenes or tumor-suppressor genes, had a negative effect on the efficacy of crizotinib in patients with ALK rearrangement NSCLC." (PMID 32974126, 2020). "In this case, however, the tumor recurred 6 months after the operation, indicating that overexpression of ALK may play an important role in the early recurrence of GIST harboring PDGFRA mutations." (PMID 32005261, 2020). "Based on KEYNOTE‐042 (NCT02220894), pembrolizumab is approved as the first-line treatment of stage III NSCLC patients with no epidermal growth factor receptor (EGFR) or anaplastic lymphoma kinase (ALK) genomic aberrations, while also the tumour must express PD-L1 (TPS ≥1%)." (PMID 33574895, 2020). "ALK rearrangements might be promptly detected in tumor tissue using fluorescence in situ hybridization (FISH), immunohistochemistry (IHC), reverse transcription-polymerase chain reaction (RT-PCR), or next-generation sequencing (NGS)." (PMID 33352844, 2020). "This histological profile is also typical of tumours harbouring an ALK translocation." (PMID 31598903, 2020). "Different methods can be used to detect ALK rearrangements in tumor tissues." (PMID 37362555, 2020). "Although the IHC positivity implies their expression in cancer cells, future studies were needed to confirm whether these rare ALK fusions could form functional products in the tumor." (PMID 33363027, 2020). "Similarly, an ALK fusion was noted in the CTCs, matching the patient’s primary tumor (P 17), and a 3′ deletion of RET was found in recovered CTCs from a patient with a RET rearranged tumor (P 26)." (PMID 31947893, 2020). "Since our IPM is based on tumor microenvironment-related genes, although its establishment is related to EGFR mutation, ALK translocation, ROS1 translocation, and BRAF mutation, it is applicable to all patients with or without these mutations in stage I-II LUAD." (PMID 33585210, 2020). "No statistical difference in overall survival was observed when comparing NB patients whose tumor harbour an ALK mutation with cases without an ALK mutation." (PMID 30778092, 2019). "Secondly, data on EGFR mutational status was only available for 42 (77.8%) patients and no data was available on other tumor mutations (e.g. ALK, ROS1, BRAF) for which targeted treatments now exist." (PMID 30973926, 2019).
tumor (continued). "PD-L1 is expressed on various cell types including T cells, B cells, NK cells, and tumor cells, the expression of which is driven by cytokines (IFN-γ) dependent and independent mechanisms, and the latter involves PTEN deletion, anaplastic lymphoma kinase (ALK) and EGFR mutation." (PMID 31134073, 2019). "We investigated whether the P36 peptide could cooperate with a TKI to kill ALK-addicted tumor cells." (PMID 30813562, 2019). "Several signaling pathways can bypass the tumor cells’ addiction to ALK." (PMID 30813562, 2019). "Fluorescent in situ hybridization (FISH) showed a rearrangement of ALK in tumor cells." (PMID 31627758, 2019). "The partial 2p gains encompassing the ALK locus were present in only 4 of 16 mutated tumours indicating that 2p gain is not a common mechanism for increasing mutated ALK copy number." (PMID 30778092, 2019). "In total, sixteen out of the 105 tumour samples (15.2%) were ALK mutant positive." (PMID 30778092, 2019). "Repotrectinib is currently under investigation in a phase 1/2 multi-center, first-in-human study to define safety, tolerability, pharmacokinetics and anti-tumor activity in patients with advanced solid tumors harboring ALK, ROS1, or NTRK1-3 rearrangements (TRIDENT-1, clinicaltrials.com)." (PMID 31852910, 2019). "Her tumor was ALK-positive NSCLC and showed dramatic regression after crizotinib treatment." (PMID 31154543, 2019). "One way to counteract ALK-addicted tumor proliferation is to target ALK downstream signaling." (PMID 30813562, 2019). "For NSCLC, NGS-based tumor-profiling multiplex gene panels, such as Oncomine Dx target test or FoundationOne CDx, have recently been approved as companion diagnostics to detect mutations of EGFR and BRAF, or fusions of ALK and ROS1 in the US." (PMID 30943926, 2019). "Additionally, 1–2% of NB tumours harbour genomic amplification of ALK, which almost exclusively occurs with MNA given their proximal association at chromosome 2p23-24." (PMID 31088252, 2019). "Because of these diverse results, the clinical impact of PD‐L1 expression on ALK‐positive NSCLC tumor cells remains unclear." (PMID 31509890, 2019). "To investigate this rigorously we have now undertaken a study of a series of 105 NB tumours to explore ALK copy number gain as well as the frequency and type of ALK mutations that may remain undetected using Sanger-based sequencing methodology." (PMID 30778092, 2019). "Studies have shown that PD-L1 expression can be induced by extrinsic stimulation such as interferon-gamma produced by surrounding tumor cells, and by the activation of intrinsic oncogenic pathways, such as STAT3, an activating EGFR mutation or ALK translocation." (PMID 30961670, 2019). "In addition, four of the 105 tumours included also had ALK gene amplification detected from previously performed SNP microarrays." (PMID 30778092, 2019). "A common reason is that in populations with EGFR, BRAF, MET, ALK and other gene mutations, it is not easy to produce new antigens of tumours, and the tumour mutation load is lower." (PMID 30862891, 2019). "In all 13 positive cases, the ALK rearrangement positive cells were distributed diffusely in all tumor areas tested, and the authors concluded that ALK rearrangement is a diffuse event and the exact percentages of positive cells have little impact on outcome of ALK inhibitor treatment." (PMID 31412611, 2019). "Finally, archival tumor imprint slides for ALK gene status assessment were available in a subset of 10 patients with 2p gain and 11 patients with MNA." (PMID 31649880, 2019). "ALK-FISH assays were performed in 1128 tumor specimens of NSCLC between January 2015 and June 2018." (PMID 31154543, 2019).
tumor (continued). "In addition to EGFR, ALK-rearrangement testing is also routine and there are a number of targeted therapies for tumours harbouring the EML4-ALK fusion gene." (PMID 30470932, 2019). "Since ALK–driven tumors are dependent for their proliferation on the constitutively activated ALK kinase, a number of tyrosine kinase inhibitors have been developed to block tumor growth." (PMID 30813562, 2019). "We observed that the majority of MYCN-amplified tumours (4 of 6) contained subclonal (<20% variant allele fraction) ALK aberrations while in MYCN-nonamplified tumours the majority of ALK mutations (8 of 10) were clonal." (PMID 30778092, 2019). "Examining the expression of ALK across all tumors samples revealed that tumor had significantly higher expression of ALK, further validating the fusion led to the activation of ALK and was a potential candidate for targeted therapy by a protein kinase inhibitor such as Crizotinib." (PMID 30255803, 2018). "Compared with ALK-wt, ALK-rearranged tumors had more spiculated and lobulated tumor margins on CT." (PMID 29732009, 2018). "Thus, if the sample contains only a few tumor cells IHC is the preferred approach (for example for evaluation of the ALK and BRAF V600E status)." (PMID 29534030, 2018). "However, all four studies used a cut-off of 50% ALK-positive immunostained tumor cells, which formed the basis of the scoring criteria used in our current study." (PMID 29535836, 2018). "With these considerations, it is not surprising that we have identified a strong correlation between the expression of ALK-I19 and the proportion of poorly differentiated areas, as well as the frequency of observing > 50% tumor areas showing strong ALK immunostaining." (PMID 29535836, 2018). "Moreover, ALK-positive NSCLC patients have a high risk of developing brain metastases, as observed in approximately 30% of cases at the time of tumor diagnosis and in 60% of patients during crizotinib treatment." (PMID 29632648, 2018). "In vivo, ALK CAR T cell efficacy was only seen when ALK expression was high on tumor cells." (PMID 30459759, 2018). "Whether Rac1 can serve as a downstream target of ALK in these cancers as well, and whether and how it contributes to invasion of tumor cells in these cancers remains to be elucidated." (PMID 30558116, 2018). "Patients bearing ALK-rearrangements tend to be never-smokers and with a low tumor mutational load and to respond poorly to PD-1 blockade." (PMID 29495603, 2018). "In Case #1, we could successfully detect resistance mutation samples from serial blood collection during ALK-TKI treatment, also could validate the data from ddPCR and NGS analysis from tumor sample." (PMID 30453899, 2018). "Additional evidence of the specificity of ponatinib’s antitumor activity was observed when ponatinib had minimal effects on an in vivo isogenic Ba/F3 tumor model dependent on oncogenic EML4-ALK in comparison with the approved ALK inhibitor crizotinib (200 mg/kg)." (PMID 30038711, 2018). "Besides, it has been showed that patients with ALK-positive tumor status seemed to have a better prognosis when treated with pemetrexed." (PMID 29318404, 2018). "However, during phase I trials it became apparent that it had substantial activity against ALK-rearranged tumours." (PMID 30065223, 2018). "A tumor containing the EML4-ALK fusion had the highest ALK expression." (PMID 30361512, 2018). "We here report a case of ALK-rearranged NSCLC that progressed after treatment with crizotinib and alectinib possibly due to L1196M secondary mutation, and subsequently manifested tumor shrinkage during treatment with ceritinib." (PMID 29796191, 2018). "In all of these reported cases, the SCLC tumor cells retained the ALK expression." (PMID 29495603, 2018). "In ALK F1174L and F1245C-mutant cell lines and patient-derived xenografts, whereas treatment with either agent alone delayed tumour growth, the combination of ceritinib and ribociclib led to a complete and sustained tumour regression." (PMID 29642598, 2018).
tumor (continued). "It is unclear whether tumors that are driven by ALK-independent resistance mechanisms also show tumor response to these drugs." (PMID 29300322, 2018). "The tumor harbored neither the epidermal growth factor receptor (EGFR) gene mutation nor the anaplastic lymphoma kinase (ALK) gene rearrangement." (PMID 29378571, 2018). "Whether IMT is reactive or neoplastic in nature has been controversial, but recently it is considered as a true tumor because of the identification of anaplastic lymphoma kinase (ALK) gene rearrangement." (PMID 30410939, 2018). "The deciphering of the host and tumor factors influencing the strength and efficacy of an autologous immune response against ALK-positive ALCL might help individual decision-making regarding consolidation therapy in the future." (PMID 29642597, 2018). "Strategies such as ALK vaccination could be effective for those with a pre-existing anti-tumor immunity, while an allogeneic blood stem cell transplantation or check-point inhibition could be effective for others." (PMID 29642597, 2018). "Similarly, standardised tumor morphology features need to be assessed in order to validate the predictive value of ill-defined tumor borders for ALK-status." (PMID 29732009, 2018). "However, both methods occasionally produce discordant results, especially in so-called borderline (BL) cases, showing ALK FISH-positive signals in 10–20% of the tumor nuclei around the cutoff (15%)." (PMID 30466405, 2018). "Consistent with other tumours of neural origin, most NB tumours express full-length ALK." (PMID 29642598, 2018). "Tumor response was observed in 100% of crizotinib naive patients, in 74% of crizotinib pre-treated patients and 83% of crizotinib-naive or crizotinib-pre-treated ALK-rearranged NSCLC with active, measurable, intracranial metastases." (PMID 29632648, 2018). "We noted a good separation between ALK specific signal on tumor epithelia and stromal background." (PMID 30326973, 2018). "Furthermore, we demonstrate regulation of MYC promoter activity by ALK in ALK+ cell lines and non-tumor NIH3T3 ectopically expressing EML4-ALK." (PMID 29507657, 2018). "The tumor was removed by surgical resection and was found to harbor an ALK fusion gene without L1196M mutation by genomic analysis." (PMID 29796191, 2018). "ALK has unique biological characteristics that are attractive for a tumor antigen." (PMID 29495603, 2018). "Different ALK fusion partners may result in different dimerization and signaling potentials and thus different tumor biology as well." (PMID 29455675, 2018). "Moreover, we have addressed the issue of auto-fluorescent lung structures by analyzing specific immunofluorescent ALK signals on tumor epithelia and on adjacent stroma on multiple individual frames laid over the tumoral structures on whole sections." (PMID 30326973, 2018). "Our data thus support a possible tumor suppressor function for this gene and also suggests that other lesions than ALK activation may be required to induce tumor formation." (PMID 29492199, 2018). "However, patients inevitably develop resistance to ALK inhibitors leading to tumor relapse that commonly manifests in the form of brain metastasis." (PMID 29455675, 2018). "The first FDA-approved ALK inhibitor for ALK-positive metastatic NSCLC treatment in 2011, crizotinib, has shown significant improvement in progression-free survival (PFS) and tumor responses in patients with metastatic NSCLC who carry the ALK gene rearrangement." (PMID 29844259, 2018). "Among the ALK-positive samples, 3 were primary tumours sampled before treatment." (PMID 30290811, 2018). "A phase I study of crizotinib in 50 patients with ROS-1 rearranged NSCLC demonstrated objective response rates (ORR) of 72% (95% CI 58–84), with a median PFS of 19.2 months (95% CI 14.4- not reached), and comparable tolerability to that reported in ALK-positive tumours." (PMID 30021993, 2018).